IDH2 (isocitrate dehydrogenase (NADP(+)) 2)
Diseases named in the same sentence as IDH2 in open-access papers (continued):
Sharing a sentence is not in itself a finding about the gene and the disease.
chondrosarcoma (continued). "Similarly, azacitidine has also been shown to reverse the differentiation block caused by mutations in IDH2 in chondrosarcoma cell lines." (PMID 37296846, 2023). "Interestingly, mutations in the IDH1 and IDH2 genes are found in 50–70% of chondrosarcomas and are implicated in chondrosarcoma tumorigenesis." (PMID 37048590, 2023). "Therefore, it was not possible to attribute the current pathology to the original chondrosarcoma on the basis of the IDH1 or IDH2 mutation." (PMID 37171609, 2023). "In addition, approximately half of chondrosarcoma cases carry an IDH1 or IDH2 mutation, and therefore mutational testing can be helpful to verify the diagnosis and to exclude chondroblastic osteosarcoma." (PMID 35875137, 2022). "Recently, researchers have discovered IDH2 R140 mutation in three advanced chondrosarcoma samples." (PMID 33981605, 2021). "IDH1 and IDH2 mutated chondrosarcomas have a distinct metabolomic profile with increased lactate, the TCA intermediates succinate, fumarate, and malate, amino acids broadly and acylcarnitines compared to non-mutated cancer cells based on patient derived xenografts." (PMID 34938658, 2021). "However, IDH1/IDH2 mutations were found to be associated with longer relapse-free survival and metastasis-free survival in high-grade chondrosarcomas." (PMID 32295254, 2020). "For the patient with dedifferentiated chondrosarcoma of the distal femur who was undergoing resection, sequencing performed by Knight Diagnostic Laboratories on the resected tumor revealed IDH2 R172S (AGG>AGT) mutation." (PMID 26368816, 2015). "~54% of the dedifferentiated chondrosarcomas contain mutations in IDH1 or IDH2." (PMID 25895133, 2015). "This panel can be implemented in studies ascertaining human chondrosarcoma tumorigenesis, should provide useful tools in the ongoing search for new targeted therapies, and aid in expanding our knowledge on the role of IDH1 and IDH2 mutations in chondrosarcoma formation." (PMID 22928481, 2012). "If IDH2 mutation impairs reductive flux of glutamine to citrate in chondrocytes, this may help to explain why citrate and α-ketoglutarate are depleted in mutant IDH2 chondrosarcomas." (PMID 33762012, 2021). "Interestingly, in chondrosarcomas, the frequency of IDH2 mutations increases with grade." (PMID 33981605, 2021). "Thus, mutations in Isocitrate Dehydrogenase-1 (IDH1) and -2 (IDH2) are found in 87% of enchondromas, up to 70% of conventional central chondrosarcomas and 54% of dedifferentiated chondrosarcomas and may drive sarcomagenic processes." (PMID 30987403, 2019). "To gain a deeper understanding of the role of IDH1/2 in chondrosarcoma metastasis, we performed detailed genomic profiling of metastatic central chondrosarcoma, with a specific focus on IDH1 and IDH2 mutations." (PMID 41299743, 2025). "In our study, IDH1 and IDH2 mutant cases were combined for outcome analysis due to a small number of IDH2 mutant chondrosarcomas in our series." (PMID 38254737, 2024).
chondrosarcoma (continued). "No mutations were detected by pyrosequencing at codon 132 of IDH1 or codon 172 of IDH2 on genomic DNA extracted from the chondrosarcoma tumor." (PMID 38236556, 2024). "One of the most common mutations observed in many cases of chondrosarcoma, including DDCS, is mutations in the IDH1 and IDH2 genes." (PMID 37568740, 2023). "The most frequent mutations found in chondrosarcomas are on isocitrate dehydrogenase (IDH) genes, on arginines R132 for IDH1 and R140/R172 for IDH2." (PMID 37046623, 2023). "To test this differential diagnosis, we examined features common to chondrosarcomas, i.e., an IDH1 or IDH2 mutation described in approximately 38.7% and 12.1% of chondrosarcoma specimens, respectively." (PMID 37171609, 2023). "In a meta-analysis of 488 patients with chondrosarcoma, IDH1 and IDH2 mutations were detected in 39% and 12% of patients, respectively." (PMID 35163019, 2022). "A potential targetable mutation of chondrosarcoma, that is, IDH gene encoding isocitrate dehydrogenase (IDH), has various isoforms including IDH1 and IDH2 and key metabolic enzymes that convert isocitrate to α-ketoglutarate." (PMID 35408900, 2022). "In chondrosarcomas, Ollier disease, and Maffucci syndrome, a high incidence of IDH1 and IDH2 mutations has been reported." (PMID 35163019, 2022). "IDH1 and IDH2 are NADP-dependent enzymes that are mutated in 38-70% of conventional and dedifferentiated chondrosarcoma cases and induce a neomorphic enzymatic activity." (PMID 34938658, 2021). "Gln levels trended to increase by 2.8-fold in mutant IDH1 chondrosarcomas and achieved statistical significance in mutant IDH2 chondrosarcomas." (PMID 33762012, 2021). "Patients with chondrosarcoma carry more than 50% of IDH1/2 mutant heterozygotes, and IDH1 R132 is the most common mutation, followed by IDH2 R172." (PMID 33981605, 2021). "These same 12 amino acids exhibited clear trends to increase in mutant IDH2 chondrosarcomas, although only 5 of these (Gly, Gln, Pro, Ser, and Asp) achieved statistical significance." (PMID 33762012, 2021). "This switch has been reported in a four-case study, and in chondrosarcoma cells harboring the double mutations IDH1-R132G/IDH2-R172V and IDH1-R132H/IDH2-R172S." (PMID 34065551, 2021). "Individual Val and Leu/Ile levels were significantly elevated in mutant IDH1 chondrosarcomas and trended to increase in mutant IDH2 chondrosarcomas." (PMID 33762012, 2021). "13C α-KG labeling was reduced at 6 h in mutant IDH1 and IDH2 chondrosarcoma cells based on measurements of citrate (M2) and pyruvate (M3) labeling." (PMID 33762012, 2021). "A different and more complex profile was found for the early TCA cycle intermediates—citrate and α-KG trended to increase in mutant IDH1 but decrease in mutant IDH2 chondrosarcomas." (PMID 33762012, 2021). "We then selected the chondrosarcoma cell line SW1353, which harbors an IDH2 mutation (R172S/+), as well as the cholangiocarcinoma cell line RBE, which harbors an IDH1 mutation (R132S/+) for combination ATR and PARP inhibitor studies." (PMID 34027408, 2021). "Eighty-seven percent of the solitary and multiple enchondromas, ~ 50% of the primary central conventional chondrosarcomas and 86% of the secondary central chondrosarcomas harbour heterozygous point mutations in IDH1 and IDH2." (PMID 31728625, 2020). "Chondrosarcomas are chemo- and radiotherapy resistant and frequently harbor mutations in isocitrate dehydrogenase (IDH1 or IDH2), causing increased levels of D-2-hydroxyglutarate (D-2-HG)." (PMID 31810230, 2019). "Sequencing analysis of common mutations in chondrosarcoma identified point mutations in IDH1 (p.R132L) in CDS01 cells and IDH2 (p.R172G) in CDS17 and T-CDS17 cells which were also detected in the corresponding patient tumor samples." (PMID 30987403, 2019).
chondrosarcoma (continued). "Chondrosarcoma is a malignant cartilage-forming bone tumour in which mutations in IDH1 and IDH2 frequently occur." (PMID 29576625, 2018). "This is consistent with chondrosarcoma abnormalities, specifically mutations in either IDH1 (cytosolic) or IDH2 (mitochondrial)." (PMID 28056047, 2017). "It is noteworthy that all three IDH2 mutations were of IDH2-R172S (AGG>AGT), which is also frequently observed in chondrosarcomas." (PMID 24403254, 2013). "We here present three chondrosarcoma cell lines, one carrying an IDH1 R132C mutation, one carrying an IDH2 R172W mutation, and one wild type for IDH mutations with stable karyotypes and steady growth patterns." (PMID 22928481, 2012). "Our study posits that initiating driver mutations in IDH1 or IDH2 in cartilaginous tumors are not required for the persistence of chondrosarcoma." (PMID 41299743, 2025). "The main difference between these two chondroid neoplasms is that IDH1 and IDH2 mutations, which are frequently found in chondrosarcomas, are not detected in chordomas." (PMID 38248076, 2024). "Mutations in the IDH1 and IDH2 genes were shown to cause vulnerability to PARP inhibition in other cancer types; however, talazoparib showed variable sensitivity in a panel of conventionally cultured chondrosarcoma cell lines." (PMID 36729612, 2023). "Integrated methylation and gene expression analysis revealed distinct IDH1/IDH2-associated methylation and transcriptional profiles as early events in DDCS, which may underlie the pathogenesis of dedifferentiation in chondrosarcomas." (PMID 36926116, 2023). "IDH2 is present in 22% of high-grade chondrosarcomas and only about 7% in low-grade tumors." (PMID 33981605, 2021). "Genetically, two main groups of chondrosarcomas exist: central chondrosarcomas, characterized by mutations in the isocitrate dehydrogenase genes IDH1 and IDH2, and secondary peripheral chondrosarcomas, characterized by alterations in the exostosin glycosyltransferase 1 (EXT1) and 2 (EXT2) genes." (PMID 32295254, 2020). "To evaluate the functional role of IDH1/2 mutations we used a chondrosarcoma cell line panel including five IDH1/2 wildtype, three endogenous IDH1 mutant and two endogenous IDH2 mutant cell lines, originating from conventional central as well as dedifferentiated chondrosarcomas." (PMID 25895133, 2015). "In chondrosarcoma and intrahepatic cholangiocarcinoma, the R132C alteration in IDH1 is the most frequent mutation, while in angioimmunoblastic T-cell lymphoma mutations in IDH2 are predominant." (PMID 24529257, 2014). "This is puzzling as the driver mutation in human central chondrosarcoma is IDH1 or IDH2, while in peripheral chondrosarcomas this is not known, but no indication for involvement of Fos is found." (PMID 23880362, 2013). "Majority of chondrosarcomas are associated with a number of genetic alterations, including somatic mutations in isocitrate dehydrogenase 1 (IDH1) and IDH2 genes, but the downstream effects of these mutated enzymes on cellular metabolism and tumor energetics are unknown." (PMID 33762012, 2021). "Considering G3 conventional chondrosarcomas, EPHA2 expression was lower in the IDH1-mutated samples when compared to the IDH1 wild-type samples (* p < 0.05), while the opposite was observed with respect to the IDH2 mutations (higher EPHA2 expression in IDH2-mutated samples; * p < 0.05)." (PMID 34831119, 2021). "This review focuses on metabolic changes in chondrosarcoma, and the relationship between signaling via isocitrate dehydrogenase 1 and 2 (IDH1 and IDH2), hedgehog, PI3K-mTOR-AKT, and SRC, as well as histone acetylation and angiogenesis." (PMID 34938658, 2021).
chondrosarcoma (continued). "The combination of the histone deacetylase inhibitor, SAHA (suberoylanilide hydroxamic acid), and the DNA hypomethylating agent decitabine was tested on chondrosarcoma IDH wild type, IDH1 mutant and IDH2 mutant cell lines in vitro and in vivo." (PMID 32707689, 2020). "Molecular analysis of the conventional chondrosarcoma component for IDH1 and IDH2 was possible in all cases." (PMID 31297850, 2019). "The amino acid-derived acylcarnitines, C5:1 and C4-OH were significantly elevated in mutant IDH2 chondrosarcomas compared with non-mutant tumors." (PMID 33762012, 2021). "IDH mutation status is not related to overall survival, but IDH2 mutation is associated with longer recurrence-free survival (RFS) and metastasis-free survival (MFS) in high-grade chondrosarcomas." (PMID 33981605, 2021). "Here, we profiled over 69 metabolites in 17 patient-derived xenografts by targeted mass spectrometry to determine if metabolomic differences exist in mutant IDH1, mutant IDH2, and non-mutant chondrosarcomas." (PMID 33762012, 2021). "Although organic acids in mutant IDH1 and mutant IDH2 chondrosarcomas did not cluster separately from one another, they clustered separately from the non-mutant group." (PMID 33762012, 2021). "The three chondrosarcomas of patients with Ollier syndrome (100%) harbored a mutation of IDH1, and all 3 cases shared the same mutation: R132C(TGT); none of the patients presented IDH2 mutation." (PMID 37752419, 2023). "One patient with Maffucci’s syndrome had a metacarpal chondrosarcoma IDH1wt and IDH2 not evaluable." (PMID 37752419, 2023). "Specifically, we compared metabolomic profiles of 4 IDH non-mutant chondrosarcomas with 8 mutant IDH1 and 5 mutant IDH2 chondrosarcomas using targeted gas chromatography-mass spectrometry (GC/MS) and flow-injection tandem mass spectrometry (MS/MS) methods." (PMID 33762012, 2021).
astrocytomas (84 papers, 2011 to 2026). "Concerning the spectrum of IDH-mutant gliomas, diagnosis of an IDH-mutant astrocytoma requires histopathological findings consistent with an infiltrating diffuse glioma with an IDH1/IDH2 mutation and ATRX loss/mutation or exclusion of 1p/19q codeletion." (PMID 37658995, 2024). "IDH-mutant astrocytoma grade 4 was defined as a diffusely infiltrative astrocytic glioma with an IDH1 or IDH2 mutation that exhibited microvascular proliferation or necrosis, CDKN2A/B homozygous deletion, or any combination of these features." (PMID 39457569, 2024). "In IDH-mutant astrocytoma, IDH2 mutation is quite rare and biological mechanisms underlying tumor progression in IDH2-mutant astrocytoma remain elusive." (PMID 38012788, 2023). "Oligodendroglioma (ODG) and astrocytoma are both classified by mutations in IDH1 or IDH2 (IDH) with the former also harboring 1p19q codeletion and the later retaining 1p19q." (PMID 35526077, 2022). "Here, we describe a case of a concurrent IDH1 and IDH2 mutations in a patient with a CNS WHO grade 3 astrocytoma, with prolonged time to recurrence." (PMID 36286062, 2022). "In adults, mutations in IDH1 or IDH2 confer a significant survival benefit in histologically lower-grade astrocytomas compared to their IDH-wildtype counterparts, and as such, is the most important prognostic factor in this group." (PMID 32640746, 2020). "IDH2 gene mutations were detected in 28% (2/14) astrocytoma cases, 28.5% (4/14) OG and GBM 9.3% (3/32)." (PMID 33552543, 2020). "This is consistent with germline variants at 8q24.21, which are associated with IDH1- IDH2 mutated astrocytoma and oligodendroglial tumors." (PMID 31968687, 2020). "The United States Food and Drug Administration (FDA) and the Australian Therapeutic Goods Administration (TGA) recently approved one such agent, vorasidenib, for adult and pediatric patients 12 years and older with grade 2 astrocytoma or oligodendroglioma with a susceptible IDH1 or IDH2 mutation." (PMID 39876890, 2024). "Notably, IDH1 and IDH2 gene mutations serve as a hallmark genetic alteration in astrocytomas linked to CIN." (PMID 39227895, 2024). "Additionally, recent studies uncovered somatic mutations in the two IDH isoforms, IDH1 and IDH2, which occur at high frequencies in cancers, including gliomas, astrocytomas, chondromas and acute myeloid leukemia (AML)." (PMID 25015087, 2014). "Notably, mutations in IDH1 and IDH2 are common driver mutations in low grade gliomas, a subset of which can progress to grade IV astrocytomas, are distinct from IDH wildtype GBMs, and represent a parallel disease process with likely alternative mechanisms of evolution." (PMID 33807183, 2021). "In presence of a consistent morphology, it is necessary to exclude a IDH1/IDH2 mutation and thus the diagnoses of an IDH-mutant astrocytoma or IDH-mutant, 1p/19q-codeleted oligodendroglioma." (PMID 37658995, 2024). "Mutations in genes coding for IDH1 or IDH2 (isocitrate dehydrogenases) occur frequently in oligodendroglioma WHO grades 2, 3 and astrocytoma grades 2, 3, 4 resulting in global changes in DNA methylation." (PMID 38711090, 2024). "We also established the first IDH2-mutant astrocytoma xenograft model derived from progressed disease." (PMID 38012788, 2023). "Our data reveal a molecular mechanism of how genomic alterations promote tumor progression and xenograft formation in IDH2-mutant astrocytoma." (PMID 38012788, 2023). "Consistent with parent recurrent tumor cells, amplifications of CDK4 and MDM2 and PDGFRA gain were found, while CDKN2A/B was identified as homozygous deletion in the xenografts, qualifying for integrated diagnosis of astrocytoma, IDH2-mutant, CNS WHO grade 4." (PMID 38012788, 2023). "In this report, we demonstrate the first novel IDH2-mutant patient-derived xenograft model established from a progressed recurrent astrocytoma, IDH2R172K mutant, CNS WHO grade 3." (PMID 38012788, 2023).